CD14 (CD14 molecule)
Diseases named in the same sentence as CD14 in open-access papers (continued):
Sharing a sentence is not in itself a finding about the gene and the disease.
Hypertension (21 papers, 2012 to 2025). The presence of chronic increased pressure in the systemic arterial system. "In this study, we investigated the association of rs2569190A>G in CD14 with cardiovascular disease risk factors (hypercholesterolemia and hypertension) in 460 individuals from the general Lebanese population (Middle Eastern multiethnic population)." (PMID 31671579, 2019). "We found significant inverse linear associations between several cognitive domains and CD14+CD16+ monocyte transmigration in those with hypertension and those with DM, for which higher mature monocyte transmigration correlated with lower T scores in several cognitive domains." (PMID 39253970, 2024). "Given the interrelationship of hypertension and DM to cardiovascular disease, a limitation in our study is that we were not powered to assess the impact of cardiovascular disease on the association between CD14+CD16+ monocyte transmigration and cognition." (PMID 39253970, 2024). "Our results suggest that, in PWH with hypertension or DM, entry of CD14+CD16+ monocytes across the BBB into the CNS contributes to CNS dysfunction." (PMID 39253970, 2024). "In the previous section, it was stated that soluble markers such as CD14 were found to be elevated in PWH with hypertension, with upregulation of ENaC, and with high-salt concentration." (PMID 36093171, 2022). "In fact, soluble CD14 has been found to be elevated in PWH with hypertension, although the contribution of ENaC to these pathoimmune responses in PWH remain to be studied." (PMID 36093171, 2022). "A recent study has shown that signals from the activated endothelium in hypertension induces conversion of classical CD14++/CD16low monocytes to CD14++CD16+ intermediate monocytes." (PMID 34698811, 2021). "Patients with a higher number (above 25th percentile) of CD34+/KDR+ and CD34+/VE-cadherin+ and lower of CD14+/endoglin+ cells (equal or below 75th percentile) were younger, with less years since diagnosis of hypertension, and with lower BP." (PMID 29304136, 2018). "Larger studies are needed to determine whether there are significant statistical interactions between hypertension or DM with CD14+CD16+ monocyte transmigration and cognition." (PMID 39253970, 2024). "In PWH on ART, injury to the BBB by hypertension or DM may promote CD14+CD16+ monocyte entry, a potential synergistic mechanism contributing to HIV-NCI." (PMID 39253970, 2024). "Additionally, we observed a significant effect of MetS (p = 0.006) and high blood pressure (p = 0.012) on the increase of cystatin C levels, and MetS (p = 0.024) and glucose (p ≤ 0.001) on the increase of CD14." (PMID 35846887, 2022). "Since miR-145 is highly expressed in VSMCs, but almost undetectable in ECs, we chose to study circulating CD14+ monocyte cells in order to evaluate the behavior of this miR in arterial hypertension at baseline and after an anti-hypertensive treatment was started." (PMID 34440064, 2021). "We found that the percentages of CD14++CD16− and CD14+CD16+ subset levels were not significantly differed between normotensive control subjects and patients with essential hypertension (57±6% vs 50±5% for CD14++CD16−; and 12±2% vs 13±2% for CD14+CD16+; each n = 11, P>0.05)." (PMID 22438881, 2012). "The average level of CD14+IL-10+ cells consistently differed between the groups: control—0.77; IQR 1.09, hypertension—68.65; IQR 7.52 and preeclampsia—55.68; IQR 31.02." (PMID 41463130, 2025). "On the other hand, in our CKD patients, we found a direct association of RWT, a measure of left ventricular concentricity broadly used as an index of LVH, with CD14++CD16− monocytes count, whereas the correlation with arterial hypertension was lost at multivariate analysis." (PMID 39273110, 2024). "Thus, the inflammatory processes in hypertension and DM in PWH on ART may further promote monocyte activation, making CD14+CD16+ monocytes even more prone to infiltrate the CNS." (PMID 39253970, 2024).
multiple myeloma (21 papers, 2008 to 2025). "Bolzoni M and co-workers further interestingly reported that sorted bone marrow CD14+ CD16+ cells from myeloma patients were more pro-osteoclastogenic than CD14+ CD16− cells in cultures ex vivo." (PMID 37894425, 2023). "Studies in precursor MM states (including MGUS and smoldering MM) have demonstrated impaired HLA-DR expression on CD14+ monocytes, which was noted to promote in vitro myeloma cell growth and suppress T-cell activation." (PMID 37752130, 2023). "CD16 antigen has been proposed as a marker of osteoclast precursors in psoriatic arthritis or in Multiple Myeloma: CD14+CD16+ cells were, in fact, more prone to differentiate toward osteoclasts, at least in these two diseases." (PMID 36497460, 2022). "Across patients, we detected the most pronounced interactions of myeloma cells with the myeloid lineage, in particular with CD14+ and CD16+ monocytes." (PMID 34845188, 2021). "CD14+/CD16+ cells have been linked with erosive bone diseases, such as psoriatic arthritis and multiple myeloma." (PMID 31130968, 2019). "We first compared the relative levels of circulating total CD14+ monocytes (percentage of total leukocytes) and the various monocyte subsets (percentage of total monocytes) for 18 newly diagnosed myeloma patients (patients 1–18) and the 17 healthy controls." (PMID 31703617, 2019). "DCs were differentiated either from CD14+ cells obtained from patients with multiple myeloma or from a human monocytic cell line." (PMID 28881793, 2017). "At the same time, we performed co-cultures of human CD14+ monocytes with primary human CD138+ cells purified from myeloma patient BM aspirates." (PMID 25257302, 2014). "Additionally, it was demonstrated that the number of bone marrow CD14+ CD16+ cells was higher in patients with active myeloma than in those with monoclonal gammopathy of undetermined significance." (PMID 37894425, 2023). "A recent clinical study has shown that the CD14+ monocytes from multiple myeloma patients could be induced to differentiate into functional DCs by culturing them with the cytokine cocktail consisting of GM-CSF, IL-4, IL-6, TNF-α and IL-1β for use in cancer immunotherapy." (PMID 18533025, 2008). "Primary human CD14+ monocytes infected with oncolytic measles virus and administered intravenously to mice with KAS6/1 human myeloma xenografts prolonged survival of mice with disseminated human myeloma." (PMID 30781349, 2019). "Moreover, we infected the bone marrow mononuclear cells obtained from myeloma patients and we checked the BVDV effect on different cell populations, defined by CD138, CD14, CD3, CD19, and CD56 expression evaluated by flow cytometry." (PMID 32653014, 2020). "In this study, AREG enriched MM1.S multiple myeloma cell and multiple myeloma patient-derived bone marrow EVs promoted both RAW 246.7 and primary human CD14+ cell osteoclast differentiation, through EGFR activation, a 1.5-fold increase in MM9 protein expression and an increase in TRAP staining." (PMID 33143170, 2020).
prostate carcinoma (21 papers, 2011 to 2024). A carcinoma that arises from epithelial cells of the prostate gland. "CX3CR1 on CD14+ CD16− monocyte was identified through IVW analysis to be positively associated with the risk of prostate cancer (OR = 1.0024, 95%CI:1.0007–1.0040, p = 0.0060)." (PMID 38566827, 2024). "Our study identified HLA DR on CD14- CD16-, CD14+ CD16- monocyte %monocyte, and HLA DR on plasmacytoid Dendritic Cell as risk factors for the incidence of prostate cancer." (PMID 38405157, 2024). "In a study on MDSCs and prostate cancer, cancer patients had an increased proportion of M-MDSCs (defined in this study as cells with CD14+ characteristics, as the gating of MDSCs differs in each article) compared to controls." (PMID 38611064, 2024). "This study aims to determine if the differential transcriptomic profiles of CD14+ and CD2+ cell populations are associated with features of adverse pathology in early stage, clinically localized prostate cancer." (PMID 34685549, 2021). "In fact, by evaluating the frequency of MDSCs in the blood of prostate cancer patients the CD14+HLA-DRlow monocytic subset result to be augmented compared with sex- and age-matched healthy donors, whereas it is decreased after ADT." (PMID 32849585, 2020). "We observed that TLR2, TLR6, and CD14 mRNA were expressed in prostate epithelial cell lines as well as in prostate cancer cell lines, and that these mRNAs were directly related to intracellular signaling upon stimulation with LTA in the human prostate." (PMID 26649771, 2015). "Expression of TLR1-10, MyD88 and CD14 in prostate cancer cells, LNCaP, PC3 and DU145, was studied by RT-PCR." (PMID 24966802, 2014). "Our study identified two immune cell phenotypes significantly associated with the risk of prostate cancer, namely CD25 on naive-mature B cells (OR = 0.998, 95% CI, 0.997-0.999, P = 2.33E-05, FDR = 0.017) and HLA DR on CD14- CD16- cells (OR = 1.001, 95% CI, 1.000-1.002, P = 8.01E-05, FDR = 0.03)." (PMID 38405157, 2024). "The majority of the studies provided information for the following surrogate markers: CD14 (prostate cancer 8/17 studies, RCC 7/12 studies), HLA-DR (prostate cancer 11/17, RCC 7/12), CD86 (prostate cancer 11/17, RCC 8/12), and CD83 (prostate cancer 9/17, RCC 9/12)." (PMID 21533099, 2011). "CRD domain of SP-D is known to interact with CD14, TLR-2, TLR-4, EGFR, and SIRPα that are reported to be present on prostate cancer cells and normal prostate tissues." (PMID 31355132, 2019). "We showed that prostate cancer cell lines differentially express TLR1-10, MyD88 and CD14 transcripts." (PMID 24966802, 2014). "In patients with histologically confirmed OSCC, breast and prostate cancers, blood samples before surgery revealed significant elevated levels of Apo10 and TKTL1 in CD14/CD16 positive monocytes compared to blood donors." (PMID 24304513, 2013). "Currently, there is no dedicated study on the specific mechanism of HLA DR on CD14- CD16- in the development of prostate cancer." (PMID 38405157, 2024). "Therefore we examined and compared expression of TLR1-10, MyD88 and CD14 and functional responsiveness to TLR-2 and 4 ligands in well-established prostate cancer cell lines." (PMID 24966802, 2014). "Indeed, no detectable levels of surface CD14 was found in prostate cancer lines." (PMID 24966802, 2014). "These primary prostate cancer stromal cells or PrCSCs are FAP-, CD90-, CD105-, and CD73-positive in the absence of CD14, CD20, CD34, CD45, and HLA-DR expression." (PMID 23362217, 2013). "PrCSCs obtained directly from prostate cancer patients, prior to expansion in tissue culture, express CD90, CD73, and CD105 in the absence of CD14, CD20, CD34, CD45, and HLA-DR as demonstrated using an optimized flow cytometry assay." (PMID 23362217, 2013).
liver disease (20 papers, 2003 to 2026). "CD14 is a surface antigen and mediates innate immune response, CD14 controls Toll-like 4 endocytosis and is implicated in liver disease." (PMID 38167156, 2024). "On the basis of this circumstance, our aim was to investigate the influence of CD14 gene polymorphisms on the risk of development of significant liver disease due to excess alcohol exposure in the North Indian ethnic population." (PMID 36238273, 2022). "CD14 protein also plays a key role in liver disease by reducing fibrosis through degradation or clearing up collagen-I deposits." (PMID 37569584, 2023). "In our study, consistent with the RNA-seq analysis, qRT-PCR showed downregulation of CD14 with more severe liver disease." (PMID 35265561, 2022). "Consistent with the MS analysis, Western blotting showed progressive up-regulation of GELS and QSOX1 with more advanced liver disease, and progressive down-regulation of CD14 with more advanced disease." (PMID 28977922, 2017). "CD14 expression in the liver increased in many types of liver disease, including alcohol and cholestatic liver injuries in rodents." (PMID 21172039, 2010). "This raised the question if similar chemokine-pathways are activated in human liver diseases as in murine experimental models, given the substantial differences in chemokine receptor expression between murine Gr1hi and human CD14+CD16+ monocytes." (PMID 20548789, 2010). "In humans, Kupffer cells in the normal liver have a low number of CD14 molecules, but this number increases in different inflammatory liver diseases." (PMID 15540801, 2003). "The potent effect of VDR SNPs on VDR expression levels may play a role in liver disease progression, considering the observed inverse relationship between CD14+VDR+ cell levels and MELD score in the cirrhotic patients in our study." (PMID 37511164, 2023). "Other studies using animals in which the genes for CD14 were removed or which lacked LBP demonstrated that signaling processes mediated by the LPS receptor were critical to the development of liver disease associated with chronic alcohol administration." (PMID 15540801, 2003). "In contrast, undifferentiated CD14+ monocytes can exacerbate liver disease, as shown by CCR2-mediated blockade of monocyte recruitment in models of liver disease." (PMID 28673774, 2017). "Study finds CD14-positive EVs are a novel biomarker of HCC and cholangiocarcinoma liquid biopsy that permit a non-invasive assessment of the presence and possible extent of these cancers in patients with advanced liver diseases." (PMID 37090718, 2023). "In patients with liver diseases, non-classical monocytes (expressing CD14 and CD16) have been suggested as the main cellular source of suPAR in the setting of acute liver failure." (PMID 31061709, 2019). "Therefore, although predominantly M1, here we confirm the coexistence of both M1 and M2 phenotypes among CD14+ blood monocytes stimulated with LPS/IFNγ in our model of EADs without advanced liver disease." (PMID 37760011, 2023). "We found highly homogeneous expression of CD14 and CD16 in infused product between alcohol-related and non-alcohol-related liver disease groups." (PMID 39794616, 2025).
lymphoma (20 papers, 2015 to 2025). A malignant (clonal) proliferation of B- lymphocytes or T- lymphocytes which involves the lymph nodes, bone marrow and/or extranodal sites. "However, the underlying mechanism by which CD14+HLA-DRlow/− monocytes develop in lymphoma is unknown." (PMID 26230952, 2015). "CD14+CD45+ monocytes were more than double increased, while platelet–monocyte aggregates (CD14+CD45+CD41+) were 5–10-fold increased in lymphomas than in healthy volunteers." (PMID 40076681, 2025). "Research should also explore how CD8+CD20+ T-cells or CD8+CD14+ T-cells interact with other immune cells in the pre-lymphoma microenvironment." (PMID 41148820, 2025). "The number of all CD14+ monocytes was significantly elevated in dogs with lymphoma RG (1781 ± 709.9) when compared to NRG dogs (966.3 ± 551.7) and healthy individuals (812.2 ± 346.2)." (PMID 36009726, 2022). "Although CD14 expression was abundant in some patient samples, the number of CD14+ cells was a rare event in the tumor microenvironment of the vast majority of lymphoma patients." (PMID 31611550, 2019). "In vitro enrichment of Mo/MΦs using a negative selection human monocyte enrichment kit plus additional depletion of lymphoma cells produced similar results and the three subsets of Mo/MΦs (CD14+SIRPαhi, CD14−SIRPαlow, and CD14−SIRPαneg) were again identified." (PMID 31611550, 2019). "Immunofluorescent staining in FL lymphoma tissue showed that while the majority of CD14+ cells were located around follicles, SIRPα+ cells resided both inside and outside of the follicles." (PMID 31611550, 2019). "Only one finding suggested the relationship between HSP-27 and monocytic myeloid suppressor CD14+HLA-DRlow/neg cells in lymphoma." (PMID 31355298, 2019). "Compared to peripheral blood, lymphoma biopsies had lower numbers of CD14+SIRPαhi cells, and increased numbers of CD14−SIRPαneg cells, respectively." (PMID 31611550, 2019). "The frequency of total SIRPα+ and CD14+ cells were significantly higher in patients with follicular grade 1/2 lymphoma by histology at diagnosis (Dx) than patients with FL grade 3a/3b." (PMID 31611550, 2019). "We found that lymphoma B cells produce IL-10 and supernatants from cultured lymphoma cells increased the CD14+HLA-DRlow/− population." (PMID 26230952, 2015). "Next we tested the effect of endogenous IL-10 production by lymphoma cells on HLA-DR expression on CD14+ monocytes." (PMID 26230952, 2015). "We found that the supernatants from lymphoma MNCs downregulated the HLA-DR expression on CD14+ monocytes." (PMID 26230952, 2015). "Little is known about the mechanisms involved in the regulation of HLA-DR on monocytes leading to increased numbers of CD14+HLA-DRlow/− cells in cancer, especially in lymphoma." (PMID 26230952, 2015). "To do this, we collected supernatants from MNCs of lymphoma tissues or cell lines and cultured CD14+ monocytes with these supernatants." (PMID 26230952, 2015). "Supporting this finding, we found that the absolute numbers and percentages of CD14+HLA-DRlow/− monocytes were significantly higher in lymphoma patients than in healthy donors." (PMID 26230952, 2015). "Additionally, flow cytometry was used to assess the frequency of CD14+ monocytes expressing VISTA in PBMCs from 65 lymphoma patients and 37 healthy donors." (PMID 38553748, 2024). "These CD169+ cells were also positive for CD14 (monocyte/macrophage marker), and it has been hypothesized that the CD169+/CD14+ cells observed in the splenic cords of splenic marginal zone lymphomas might have a dendritic cell differentiation potential." (PMID 37372147, 2023). "Less than 1% of all cells were CD14+ in lymphoma and LN samples." (PMID 32017809, 2020). "To further determine whether CD14 expression is only present in a subset of Mo/MΦs, we also stained lymphoma sections for CD163, a high-affinity scavenger receptor also expressed on Mo/MΦs." (PMID 31611550, 2019).